PLXNB2 (plexin B2)
Description:
Cell surface receptor for SEMA4C, SEMA4D and SEMA4G that plays an important role in cell-cell signaling (By similarity). Plays a role in glutamatergic synapse development and is required for SEMA4A-mediated excitatory synapse development (By similarity). Binding to class 4 semaphorins promotes downstream activation of RHOA and phosphorylation of ERBB2 at 'Tyr-1248' (By similarity). Also acts as a cell surface receptor for angiogenin (ANG); promoting ANG endocytosis and translocation to the cytoplasm or nucleus. Required for normal differentiation and migration of neuronal cells during brain corticogenesis and for normal embryonic brain development (By similarity). Regulates the migration of cerebellar granule cells in the developing brain (By similarity). Plays a role in RHOA activation and subsequent changes of the actin cytoskeleton. Plays a role in axon guidance, invasive growth and cell migration. May modulate the activity of RAC1 and CDC42 (By similarity).
Synonyms: KIAA0315; MM1; PLEXB2; lncFAL; Nbla00445; dJ402G11.3
Tractability: Antibody: UniProt places it where antibodies can reach, with high confidence; its Gene Ontology location is reachable by antibodies, with high confidence; UniProt predicts a signal peptide or a membrane-spanning region. PROTAC: ubiquitination databases record sites on it; its protein half-life has been measured.
Gene: Protein-coding gene on chromosome 22 (50,274,978 to 50,307,695, reverse strand). Ensembl gene ENSG00000196576.
Subcellular location: Cell membrane
Gene Ontology:
Molecular function: protein binding; signaling receptor activity; transmembrane signaling receptor activity; semaphorin receptor activity
Biological process: homophilic cell-cell adhesion; positive regulation of neuron projection development; positive regulation of translation; receptor-mediated endocytosis; brain development; excitatory synapse assembly; negative regulation of cell adhesion; neural tube closure; neuroblast proliferation; positive regulation of axonogenesis; regulation of cell migration; regulation of cell shape; regulation of GTPase activity; regulation of neuron migration; regulation of protein phosphorylation; semaphorin-plexin signaling pathway; synapse assembly; positive regulation of cell projection organization; regulation of neuron projection development; regulation of protein metabolic process
Cellular component: cell surface; extracellular exosome; plasma membrane; semaphorin receptor complex
Genetic constraint (gnomAD): Loss-of-function variants: 85 observed, 186.88 expected, observed/expected ratio (o/e) 0.45, 90% interval 0.38 to 0.55. The upper end of that interval is the gene's LOEUF score, 0.55, which puts it in group 2 of 6, group 1 being the genes least tolerant of losing a copy. Missense variants: 2,063 observed, 2,542.7 expected, observed/expected ratio (o/e) 0.81, 90% interval 0.78 to 0.84. Synonymous variants: 1,239 observed, 1,124.7 expected, observed/expected ratio (o/e) 1.1, 90% interval 1.05 to 1.15.
Homologues: Orthologues: chimpanzee PLXNB2 (99% identical), macaque PLXNB2 (97% identical), pig PLXNB2 (90% identical), rat Plxnb2 (88% identical), guinea pig PLXNB2 (88% identical), mouse Plxnb2 (88% identical), dog PLXNB2 (87% identical), tropical clawed frog plxnb2 (59% identical), zebrafish plxnb2a.1 (52% identical), zebrafish plxnb2b (51% identical), Drosophila melanogaster PlexA (33% identical), Drosophila melanogaster PlexB (32% identical), and 5 more. Paralogues in human: PLXNB1 (43% identical), PLXNB3 (41% identical), PLXND1 (34% identical), PLXNA4 (33% identical), PLXNA1 (33% identical), PLXNA2 (32% identical), PLXNA3 (32% identical), PLXNC1 (21% identical).
Diseases named in the same sentence as PLXNB2 in open-access papers:
PLXNB2 is named in the same sentence as 70 diseases in open-access papers, as found by Europe PMC text mining. Sharing a sentence is not in itself a finding about the gene and the disease. The quoted sentences say what the papers report.
glioma (9 papers, 2015 to 2023). A benign or malignant brain and spinal cord tumor that arises from glial cells (astrocytes, oligodendrocytes, ependymal cells). "To investigate the mechanisms underlying the link between Plexin-B2 expression and glioma malignancy, we turned to human glioma cells to study Plexin-B2′s roles in mediating cellular processes." (PMID 25762646, 2015). "Another possibility to consider is that in glioblastoma, which is the most malignant type of glioma, tumor cells may have acquired multiple mutations that provide mechanistic substitutes for high Plexin-B2 expression." (PMID 25762646, 2015). "High PLXNB2 expression has been reported in glioma and breast cancer cell lines, and has been recently examined in several primary tumor types by IHC." (PMID 38025776, 2023). "In sum, the patient survival data suggest that Plexin-B2 upregulation in glioma correlates with a poorer patient survival outlook." (PMID 25762646, 2015). "We next examined Plexin-B2 protein expression by immunohistochemistry on human glioma tissue microarray cores." (PMID 25762646, 2015). "In summary, we identified Plexin-B2 as a potential new prognostic marker for malignant glioma, and a novel drug target to curtail migratory invasion of glioma." (PMID 25762646, 2015). "Together, our studies support a role of Plexin-B2 as a potential prognostic biomarker and a novel drug target for high-grade glioma." (PMID 25762646, 2015). "When stratified for glioma types, astrocytoma patients with upregulated PLXNB2 exhibited a significantly shorter median survival than those with intermediate level (23.0 vs. 58.2 months, p<10−2)." (PMID 25762646, 2015). "Our results demonstrate that Plexin-B2 promotes glioma invasion and vascularization, and they identify Plexin-B2 as a potential novel prognostic marker for glioma malignancy." (PMID 25762646, 2015). "Correspondingly, the 5-year survival rate of glioma patients in the PLXNB2 upregulated cohort was below 20%, while it was above 40% for patients with intermediate PLXNB2 levels." (PMID 25762646, 2015). "We next investigated the in vivo function of Plexin-B2 in glioma invasive migration and growth using an orthotopic xenotransplant model." (PMID 25762646, 2015). "Plexin-B2, an axon guidance receptor important for mediating neural progenitor cell migration during development, is upregulated in gliomas, but its function therein remains poorly understood." (PMID 25762646, 2015). "Plexin-B2 protein was consistently detected at robust levels in all glioma samples; by contrast, Plexin-B1 and -B3 protein levels were highly variable between samples." (PMID 25762646, 2015). "Among the three Plexin-B receptors (B1-B3), Plexin-B2 is an apparent candidate to play a critical role in glioma growth and invasion, because it was originally cloned as a gene highly upregulated in malignant brain tumors." (PMID 25762646, 2015). "Future studies to simultaneously perturb both Plexin-B2 and Met pathways are needed to evaluate the therapeutic potential of a combinatorial treatment strategy to curb glioma growth." (PMID 25762646, 2015). "Using normal brain tissue as a baseline reference, we found elevated Plexin-B2 protein expression in the vast majority of the examined glioma specimens." (PMID 25762646, 2015). "To determine the function of Plexin-B2 in glioma cells, we focused on the ATTC lines LN229 and U87MG and the GSC line SD02, and generated stable knockdown lines using lentiviral shRNA vectors." (PMID 25762646, 2015). "Future in-depth studies with patient-derived neurosphere GSC lines such as SD02 will further elucidate Plexin-B2′s role in regulating glioma malignancy." (PMID 25762646, 2015). "We demonstrate that Plexin-B2 activation changes the actin cytoskeleton and promotes migration of glioma cells." (PMID 25762646, 2015).
glioma (continued). "We also utilized Matrigel transwell assays to measure the effect of Plexin-B2 activation on the invasive migration capacity of glioma cells to penetrate an extracellular matrix substrate." (PMID 25762646, 2015). "To explore the clinical significance of Plexin-B2 upregulation in glioma, we performed Kaplan-Meier survival analyses with the NCI/Rembrandt data platform." (PMID 25762646, 2015). "Notwithstanding, in both LN229 and U87MG glioma cells, Sema4C/Plexin-B2 signaling promotes cell migration in vitro, synergistic Met activation, and vascularization of tumor mass, thus underscoring generality of Plexin-B2 function for glioma progression." (PMID 25762646, 2015). "In this study, we show that Plexin-B2 is consistently upregulated in human gliomas and that its expression levels correlate with glioma grade and poor survival." (PMID 25762646, 2015). "Upon stimulation by Sema4C, Plexin-B2 signaling: i) alters actin cytoskeleton and cell morphology, ii) enhances glioma cell migration, and iii) promotes glioma invasive growth, in particular, along microvasculature." (PMID 25762646, 2015). "Next, we examined the effect of Plexin-B2 activation on the migration of glioma cells in a scratch wound assay." (PMID 25762646, 2015). "Combining bioinformatic analyses, immunoblotting and immunohistochemistry of patient samples, we demonstrate that Plexin-B2 is consistently upregulated in all types of human gliomas and that its expression levels correlate with glioma grade and poor survival." (PMID 25762646, 2015). "Moreover, overexpression of PLXNB2 proteins is correlated with significantly reduced median survival rate in prostate cancer, glioma, and breast cancer." (PMID 35335125, 2022). "Furthermore, PLXNB2 was identified to be a prognostic biomarker for glioma and facilitated to glioma invasion and vascularization." (PMID 34367233, 2021). "High levels of EGFR (positive in > 10% of the total living cells) in the CD45−CD105− cells was detected in 6 of 6 RMPAhigh and 13 of 16 RMPAlow gliomas analyzed; and high PLXNB2 expression in the CD45−CD105− cells was detected in 5 of 6 RMPAhigh and 11 of 16 RMPAlow gliomas analyzed." (PMID 27385209, 2016). "Targeting the Sema4/Plexin-B2 pathway may not only slow down glioma invasion, but also disrupt glioma vascularization, a critical step in tumor progression." (PMID 25762646, 2015). "Met is well known for its promigratory function in glioma cells, hence, Plexin-B2/Met interaction may further facilitate glioma migration." (PMID 25762646, 2015). "The cognate in vivo ligands for Plexin-B2 in glioma remain to be determined." (PMID 25762646, 2015). "This implies that the Plexin-B2/Met synergy may become biologically relevant when glioma cells encounter sub-threshold levels of HGF, a situation conceivably occurring at the invasive front of gliomas." (PMID 25762646, 2015). "In addition, recent analyses of glioma patient samples identified Plexin-B2 as a potential biomarker for high-grade glioma." (PMID 25762646, 2015). "Plexin-B2 knockdown hinders invasive migration of glioma cells and perturbs perivascular spreading." (PMID 25762646, 2015). "We next analyzed the NCI Rembrandt data for PLXNB2 expression among different WHO glioma types." (PMID 25762646, 2015). "The reduction in actin stress fibers and the increased formation of membrane ruffles by SEMA4C-Fc stimulation were strongly attenuated in Plexin-B2 shRNA knockdown lines, indicating that the Sema4C-triggered actin dynamics in glioma cells are mediated through Plexin-B2." (PMID 25762646, 2015). "Our study unravels for the first time a link between Plexin-B2 and glioma invasiveness." (PMID 25762646, 2015). "Here, we focused on the function of Plexin-B2 in the invasive growth of glioma." (PMID 25762646, 2015).
glioma (continued). "PLXNB2 expression was increased in all glioma types over normal brain, including oligodendroglioma and astrocytoma (grade II-III), and the highest expression levels were found glioblastoma (grade IV), indicating a correlation of PLXNB2 expression level and glioma grade." (PMID 25762646, 2015). "Among the three Plexin-B receptors, Plexin-B2 appears to be uniquely involved in glioma malignancy." (PMID 25762646, 2015). "Notably, the Rembrandt platform stratified gliomas into only PLXNB2 upregulated or intermediate groups, and did not include a PLXNB2 downregulated group (defined as <2-fold below normal), reflecting high prevalence of Plexin-B2 upregulation in gliomas." (PMID 25762646, 2015). "It is therefore likely that endothelial/glioma cell interactions might be mediated through Sema4C/Plexin-B2 signal transduction." (PMID 25762646, 2015). "However, no significant changes in the rates of proliferation or apoptosis in U87MG gliomas with Plexin-B2 knockdown were observed at 2 weeks after transplantation, indicating that effects of Plexin-B2 knockdown on tumor growth had occurred earlier." (PMID 25762646, 2015). "Other classes of Plexins, Plexin-As in particular, have also been implicated in regulating glioma cell migration; whether they act in parallel of Plexin-B2 or regulate distinct aspects of glioma cell motility awaits future study." (PMID 25762646, 2015). "In addition, reverse signaling of Sema4s has been reported, it is thus conceivable that Plexin-B2 expressed by glioma cells may signal through Sema4C on endothelial cells to promote vascular proliferation." (PMID 25762646, 2015). "Besides directly controlling tumor cell motility, Plexin-B2 may also promote invasive glioma growth by influencing cell-cell interactions between glioma and stromal cells in the tumor microenvironment." (PMID 25762646, 2015). "Furthermore, previous studies have established Plexin-B2 as an important regulator for migration of both embryonic and adult neural precursor cells, but whether Plexin-B2 plays a similar role in glioma invasion is unclear." (PMID 25762646, 2015). "To determine downstream effectors of Plexin-B2 in glioma cells, we first investigated whether Plexin-B2 signaling activates Rho GTPases, which are mediators of invasive migration in glioma cells and known downstream effectors of Plexin-Bs in non-neuronal cell lines." (PMID 25762646, 2015). "Though gliomas with RMPAlow signature contained fewer CD45+ cells and CD105+ cells, CD45+ cells in these gliomas also expressed VEGFR1, KDR, EPHB4 and PLXNB2." (PMID 27385209, 2016). "In our orthotopic glioma transplant studies, vascularization of LN229 and U87MG transplants was markedly reduced with Plexin-B2 knockdown." (PMID 25762646, 2015). "Our findings suggest a potential synergy between Plexin-B2 and the RTK Met in glioma cells, which echoes earlier findings on Plexin-B1/Met interaction in promoting tumor growth and invasion of breast cancer and other non-CNS carcinoma cells." (PMID 25762646, 2015). "The mechanism of EGCG+HC may be through the downregulation of SEMA3A and SEMA3F transcript expression which may play some roles in inhibiting the glioma proliferation and halts invasion via Plexin A1 (PLXNA1) and B2 (PLXNB2) receptors." (PMID 35392560, 2022). "Similarly, PLXNB2 which was found to be downregulated with EGCG+HC in this study, is recognized a potential biomarker for high-grade glioma." (PMID 35392560, 2022). "These genes include HMGA1 in glioma, AKT1 in glioma, PTC, GC, and HCC, HEMGN in PTC, APLN and MMP19 in GC, WNT1 in CRC, NUPR1 in CRC and OSCC, LY6E and CTSB in CHOL, KLK4 and PLXNB2 in OC, and HDAC4 and STAT3 in SaOS." (PMID 36175921, 2022). "To rule out a potentially confounding effect from a reduced cell proliferation rate, we confirmed that Plexin-B2 knockdown did not significantly affect the proliferation rates of glioma cells in vitro." (PMID 25762646, 2015).
glioma (continued). "The signaling partners and downstream effectors of the Plexin-B2 pathway in glioma are also not understood." (PMID 25762646, 2015). "We found that Plexin-B2, but not -B1 or -B3, was consistently detectable in all glioma cell lines examined, in line with our findings in patient glioma specimens." (PMID 25762646, 2015). "These miR-637-targeted genes include HMGA1, CDK6, and WNT7A in glioma, HEMGN in PTC, APLN in GC, USP21 in HCC, LY6E and CTSB in CHOL, NUPR1 in OSCC and MM, HDAC4 in SaOS, ABL1 in CML, KLK4 in OC, PLXNB2 in OC, AKT1 in TNBC, PTC, and HCC, AKT3 in TNBC, and RING1 in CCa." (PMID 36175921, 2022). "In Plexin-B2 knockdown SD02 transplants, however, tumor cells appeared in random orientations relative to the microvessels, and a significantly smaller fraction of tumor cells were attached to the microvessels, supporting a model that Plexin-B2 promotes perivascular migration of glioma cells." (PMID 25762646, 2015). "Plexin-B2 knockdown resulted in smaller tumor masses of U87MG but not LN229 transplants, suggesting that LN229 glioma cells might rely less on perivascular spread but more on other processes to gain access to nutrition and pro-growth signaling." (PMID 25762646, 2015).
ovarian carcinoma (8 papers, 2019 to 2024). A malignant neoplasm originating from the surface ovarian epithelium. "PLXNB2 was previously associated with cell proliferation, invasion, and decreased phosphorylation of AKT and ERK1/2 in ovarian cancer cells." (PMID 35053566, 2022). "Circ_0013958 plays an oncogenic role in ovarian cancer by regulating the miR-637/PLXNB2 axis." (PMID 38514488, 2024). "Moreover, PLXNB2 has been described to act as oncogene in ovarian cancer cells, where a knock-down of PLXNB2 led to decreased cell viability and invasion." (PMID 32188026, 2020). "Moreover, the authors demonstrated the existence of an association between miR-126-3p overexpression and PLXNB2 downregulation on the cell-growth viability, cell colony, and cell invasion, suggesting that miR-126-3p affects ovarian cancer’s progression by direct regulation of PLXNB2." (PMID 35053566, 2022).